MIR449C (microRNA 449c)
Synonyms: hsa-mir-449c; mir-449c
Gene: MicroRNA gene on chromosome 5 (55,172,262 to 55,172,353, reverse strand). Ensembl gene ENSG00000251856.
Pathways (Reactome):
Signal Transduction: Pre-NOTCH Transcription and Translation
Gene Ontology:
Biological process: miRNA-mediated post-transcriptional gene silencing